EGFR (epidermal growth factor receptor)
Diseases named in the same sentence as EGFR in open-access papers (continued):
Sharing a sentence is not in itself a finding about the gene and the disease.
tumor (continued). "Several previous papers present that therapeutic radionuclides, 90Y- and 177Lu-labeled anti-EGFR antibodies have the therapeutic potential to cetuximab-resistant HNSCC tumor model." (PMID 29190900, 2017). "PKM2-dependent β-catenin transactivation and CCND1 expression are instrumental in EGFR-promoted tumor cell proliferation and brain tumor development." (PMID 29299177, 2017). "If an scFv targeting EGFR is fused to this glycoprotein, the virus is then able to use EGFR as an entry receptor which improves tumor targeting." (PMID 28944214, 2017). "To conduct these experiments we selected D122 cells since they demonstrated a higher MHC-I induction after treatment with EGFRIs as compared to other EGFR-positive tumor cells." (PMID 29056908, 2017). "rE/CUS significantly inhibited the cell viability against various EGFR highly expression tumor cell lines in a dose-and time-dependent manner." (PMID 28445134, 2017). "The tumor heterogeneity metric 1/COV and SUVmax were both predictive for the EGFR mutations in NSCLC in a univariate analysis." (PMID 28881771, 2017). "Cetuximab has been shown to inhibit the proliferation of various EGFR over-expressed malignant cell lines in vitro and enhance the anti-tumor activity of several chemotherapeutic drugs or radiotherapy in mouse xenograft models." (PMID 29190900, 2017). "Imaging of EGF-Rh and EGFR-GFP fluorescence on flank tumor sections demonstrated the presence of vesicles containing both ligand and receptor in a large population of cells." (PMID 29268862, 2017). "EGFR mutation detected on FFPE tissue samples of resected specimens for CCA was an independent prognostic parameter on multivariate analysis, along with tumor stage." (PMID 28077782, 2017). "In comparison, EGFR exhibited staining of both normal and dysplastic epithelium in most cases, and importantly also a general EGFR expression in salivary gland tissue outside the tumor compartment was seen." (PMID 28841839, 2017). "The anti-EGFR CAR-T cells secreted cytokines including IL-2, IL-4, IL-6, IFN-γ, TNF-α, GM-CSF, and granzyme B in co-culture with EGFR-positive tumor cells." (PMID 28356156, 2017). "The hepatic uptake was much higher than uptake in tumour or EGFR-expressing tissues, i.e. colon and salivary gland." (PMID 28729680, 2017). "Previous studies have established that cetuximab can induce ADCC in vitro, even in tumor cells with relatively low levels of EGFR expression." (PMID 28674498, 2017). "The present study indicates that, in the presence of SO1861, tumor cells with low EGFR expression are also eliminated, finally leading to complete remission in four of five cases without adverse events." (PMID 28755527, 2017). "Similar to keratinocytes, EGFR ligand shedding and subsequent EGFR signaling are a key factor in tumor migration and invasion." (PMID 28260841, 2017). "Treatment with Mo-IPQA led to inhibition of EGFR activity in tumour cells, importantly in a manner dependent on the administered Mo-IPQA dose." (PMID 28166195, 2017). "In tumor cells with higher EGFR expression (F3II and D122), we observed a strong MHC-I upregulation after 7A7 treatment." (PMID 29056908, 2017). "Assessment of Circulating Tumor Cells as an Early Predictive Marker of Response to a First Line Treatment Based on an Anti-Human Epidermal Growth Factor Receptor (HER), Cetuximab, in Patients With Inoperable Recurrent and/or Metastatic HNSCC." (PMID 27683128, 2017). "Protein expression of total EGFR and pEGFR as well as their representative signalling transducers in primary tumour tissue samples of 87 patients with STS were detected by tissue microarray technology and immunohistochemistry." (PMID 28556791, 2017).
tumor (continued). "For tumor grade, the R value was much higher in the II-III/III group, indicating that RHBDD1 and EGFR expression was significantly associated with advanced-stage tumor grade." (PMID 28445956, 2017). "The concordance rate for detection of the T790M EGFR mutation between CTC and tumor sample was good (κ=0.70)." (PMID 29312651, 2017). "Our data demonstrate that overexpression of HCaRG inhibits RCC development and tumor angiogenesis by inactivating the proto-oncogene, ErbB2, and gene silencing of EGFR and ErbB3." (PMID 29050225, 2017). "Constitutive activation of receptor tyrosine kinase signalling is a major feature of these tumours, as illustrated by the frequent amplification of the EGFR locus." (PMID 28695888, 2017). "No tumors had very high simultaneous EGFR and ERBB2 protein expression (IHC Tumor Cell Score ≥ 2.5), while one Uro tumor had high EGFR and ERBB3 protein expression." (PMID 28388586, 2017). "Clinical predictions of anti-tumor activity were enabled by the use of tumor response data from three Phase 1 clinical trials testing combinations of EGFR, BRAF, and MEK inhibitors." (PMID 28649441, 2017). "Molecular targeting of EGFR is a promising development in FGS; however, it is dependent on the expression of EGFR in tumor cells." (PMID 27878374, 2017). "Using the TST vendor-supplied bioinformatics pipeline we were able to detect and validate by orthogonal methods known activating driver mutations in EGFR, KRAS and BRAF below 5% VAF in cases with ≥10% tumor cell content by routine pathological assessment." (PMID 28415793, 2017). "In conclusion, our data demonstrates the first approach that native glycan fragments can be measured in FFPE tissues and are associated with tumor biology and related processes such as patient outcomes and the expression of HER2 and EGFR." (PMID 28978092, 2017). "Proven effective at reducing c-Met phosphorylation, cell migration, and tumor proliferation in preclinical glioblastoma models, onartuzumab has been evaluated in phaseI/II trials in solid tumors and in combination with the EGFR inhibitor erlotinib in NSCLC." (PMID 28441771, 2017). "Again, a recent study on both cell lines and tumor specimens highlighted the importance of NGS in detecting genes potentially involved in the resistance to anti-EGFR therapy in KRAS wild-type patients." (PMID 29221448, 2017). "In this report, we identify PGE2 as a novel regulator of EGFR nuclear translocation that induces EGFR-mediated tumor cell progression." (PMID 28415726, 2017). "For example, an EGFR-specific nanobody-photosensitizer conjugate rendered tumor cells sensitive to light induced death in vitro and in an orthotopic mouse tumor model in vivo." (PMID 29213270, 2017). "Yet, 57Co-DOTA-ZEGFR:2377 provided 2-5-fold higher tumour-to-organ ratios compared to 89Zr-DFO- EGFR:2377." (PMID 28729680, 2017). "The downregulation of HER1 (EGFR) upon SATB1 knockdown is in line with previous studies in other tumor entities." (PMID 28049521, 2017). "The established metastases model is a valuable tool to reflect the clinical situation on a morphological and molecular level and serves as an ideal advanced tumor model to investigate our EGFR-targeted NIS-mediated gene therapy approach." (PMID 29190908, 2017). "Several studies have demonstrated that circulating free tumor-derived DNA (ctDNA), which can be isolated from the plasma or serum of patients with NSCLC, is feasible to assess EGFR mutation status." (PMID 28949965, 2017). "Addition of the iNOS inhibitor L-NAME significantly decreased the activation of EGFR in tumour cells co-cultured with macrophages." (PMID 28166195, 2017). "Inhibition of EGFR-dependent survival signals promotes apoptotic signals, which synergistically increase tumor cell death." (PMID 27935858, 2017).
tumor (continued). "The BsAb has more potent anti-tumor activity than combination therapy of the two parental mAbs and shows efficacy in tumors which are resistant to EGFR monotherapy and was amenable to combination therapy with tyrosine kinase inhibitors." (PMID 29138497, 2017). "It has been demonstrated that the TGFα-PE38 fusion protein was cytotoxic to EGFR-expressing tumor cells in vitro and in xenograft mouse models." (PMID 28473665, 2017). "During metastasis of GBM, the signals of epithelial growth factor (EGF) are amplified by the EGF receptor (EGFR) to promote tumor growth and survival." (PMID 29029486, 2017). "Recently a drug targeting T790M-positive tumours, osimertinib, was approved after studies showing prolongation of progression free survival in EGFR-pre-treated and progressed patients harbouring T790M." (PMID 28680534, 2017). "The median plasma cfDNA concentrations of the 93 tumor-tissue EGFR M+ and 122 tumor-tissue EGFR M- patients were 9.61 ng/mL (range 1.01-406.91) and 12.82 ng/mL (range 1.32-2302.22), respectively; this difference was statistically significant (P = 0.049)." (PMID 28052016, 2017). "In clinical practice, afatinib, a tyrosine kinase inhibitor (TKI), has been reported to inhibit EGFR phosphorylation and further suppress tumor progression." (PMID 28787001, 2017). "The hyperactivation of EGFR is known to mediate tumour growth, and consistent with this finding, small molecules and antibodies that bind to HER1, such as gefitinib, have proven anti-cancer activity." (PMID 28881753, 2017). "Both nimotuzumab and cetuximab EGFR+ tumor complex in the presence of NK and DC generate cross-presentation of TAs by DC to T cells resulting in the induction of EGFR-specific T cells in vitro." (PMID 28674498, 2017). "The increase in phosphorylated EGFR in FLCN−/− and tumour-associated mutants was most pronounced at 1 h after EGF treatment, but remained high at the 3 h time point." (PMID 28656962, 2017). "In ESCCs, we identified amplification or mutation of EGFR in 19% of tumours and alterations of PIK3CA, PTEN or PIK3R1, all of which are believed to activate the PI3K pathway, in 24% of tumours." (PMID 28052061, 2017). "We previously demonstrated that lymph node metastasis, tumor cell differentiation and perineural invasion and tumor stage are correlated with EGFR gene amplification." (PMID 28854970, 2017). "We describe a pharmacological inhibitor of LOX, CCT365623, which disrupts EGFR cell surface retention and delays the growth of primary and metastatic tumour cells in vivo." (PMID 28416796, 2017). "Based on the outcome of these future scans, one would not only be able to precisely localize EGFR+ tumors in the individual patients, but also collect valuable information on the pharmacokinetics of tumor-targeting monoclonal canine IgGs for the first time." (PMID 29137329, 2017). "We evaluated the efficacy of EGFR-TKIs via CT scanning and serum tumor marker concentrations (CEA) every 2 months." (PMID 28705152, 2017). "We have demonstrated that cRGD-siEGFR can effectively knockdown EGFR expression with high tumor uptake in vitro and in vivo." (PMID 28181832, 2017). "The EGFR (HER-1 or ErbB1), a member of the tyrosine kinase receptor family, is well-known to stimulate tumor development via autocrine loop." (PMID 29137429, 2017). "First, they accelerate EGFR turnover through ubiquitination, and curtail EGFR receptor density, enabling a reduced concentration of cetuximab to exert tumor inhibitory efficacy." (PMID 29137335, 2017). "uPAR and TF exhibited a highly tumor-specific expression pattern while EGFR also showed expression in normal tissues outside the tumor compartment." (PMID 28841839, 2017). "When EGFR is inhibited in cancer therapy, tumor cells possibly evade death by increasing MET signaling." (PMID 28456787, 2017). "This suggests a role for macrophage-intrinsic EGFR-mediated signaling in the establishment of the tumor microenvironment." (PMID 28970798, 2017).
tumor (continued). "Given the limitation of SUVmax, we chose another volume-based PET/CT parameter, metabolic tumor volume (MTV), as an alternative variable to explore the relationship between PET/CT and EGFR gene mutation status." (PMID 28422710, 2017). "Silver staining revealed nanoparticle accumulation in only MDA-MB-231 tumor tissues at 48 h post-injection of anti-EGFR-GN." (PMID 29156817, 2017). "During treatment with anti-EGFR monoclonal antibodies, emergence of RAS and other mutations can be identified in circulating tumour DNA (ctDNA) before clinically apparent disease progression." (PMID 28859058, 2017). "The pooled ORs indicated that PD-L1 expression was associated with gender, smoking status, histology, differentiation, tumour size, lymph nodal metastasis, TNM stage and EGFR mutation." (PMID 28860576, 2017). "Epithelial to mesenchymal transition (EMT), which renders cells more migratory and invasive, is also observed in EGFR TKI-resistant tumor specimens." (PMID 28969097, 2017). "Collectively, our data uncover a key mechanism by which tumor cells attain central hallmarks of cancer by PGE2-mediated EGFR nuclear localization." (PMID 28415726, 2017). "We investigated the effect of another commercially available anti-EGFR antibody nimotuzumab on HLA class I expression in tumor cell lines." (PMID 29056908, 2017). "B16 tumors were transferred into wt C57BL/6 mice, and the mice later immunized with either tumor antigen-pulsed BM-DCs or EGFR-blocking nanobodies, BM-DCs in combination with EGFR-blocking nanobodies, or alone." (PMID 28970798, 2017). "A combination of intravital imaging of tumors, high-resolution fluorescence microscopy of tumor sections and biochemical analysis demonstrated activation, ubiquitylation and endocytosis of EGFR in tumors in vivo." (PMID 29268862, 2017). "The inhibition efficacy to tumor growth dramatically improved by coupling anti-EGFR EGa1 Nbs to the surface of these micelles." (PMID 29163515, 2017). "In conclusion, the results of the present study suggest that EGFR mutation in an Asian population with NSCLC is correlated with clinical and metabolic parameters, including MTV, smoking status and tumor location." (PMID 28422710, 2017). "We found that the phosphorylated EGFR levels are reduced after treatment with MAG-EPA in tumor derived from HCT116 xenograft mice model when compared to the tumors derived from untreated control animals." (PMID 28869531, 2017). "In the H596 NSCLC xenograft model, the anti-tumor efficacy of ficlatuzumab was verified and increased with combination therapy with gefitinib and cetuximab, an EGFR inhibitor, compared with single agent treatment." (PMID 28817103, 2017). "For the patients with slow asymptomatic progression and oligoprogressive disease, the mutant EGFR remains driver gene in most of tumor clones during the disease course and thus continuing TKIs with or without local therapy is recommended." (PMID 29163853, 2017). "EGFRvIII contains an in-frame deletion in the extracellular domain of EGFR, creating a novel antigenic epitope which is exquisitely tumor-specific." (PMID 29164053, 2017). "Proof-of-concept BEAT antibodies were designed to co-target different pairs of validated tumor antigens (EGFR/HER3 and HER2/HER3)." (PMID 28450393, 2017). "Overall, these data demonstrate that lapatinib decreases tumor latency and mammary gland morphogenesis by negatively regulating the EGFR/erbB-2 and ERα signaling pathways." (PMID 28061785, 2017). "Immunohistochemistry analysis was conducted to assess the protein abundance of DACH1, CD44, Myc, Sox2, Fibronectin, Vimentin, EGFR, Ki-67 in nude mice xenograft tumor tissues with overexpression of DACH1 and the GFP controls." (PMID 28659634, 2017). "Aberrant activation or expression of EGFR leads to the promotion of proliferation, cell motility, and invasive capacity of tumor." (PMID 28057023, 2017).
tumor (continued). "miR-143 and miR-145, negatively targeting these proto-oncogenes, were down-regulated by HFD in both tumor models only in EGFR-expressing mice, indicating that epigenetic changes associated with diet-induced colon tumorigenesis require EGFR signaling." (PMID 28424679, 2017). "Because the PI3K/Akt/mTOR pathway is a signaling cascade downstream of the EGFR that stimulates cell growth and is often dysregulated in tumor cells, targeting this pathway is one potential method for overcoming resistance to anti-EGFR targeted therapy." (PMID 28536670, 2017). "Opsonization of EGFR-expressing tumor cells with the nanobody-tag rendered the tumor cells highly sensitive for attack by human peripheral blood T cells that had been transduced to express a tag-specific CAR (UniCAR T cells)." (PMID 29213270, 2017). "Studies have shown that it is highly expressed in most cancer patients, and that abnormal EGFR signaling pathways play an important role in tumorigenesis, tumor progression, and metastasis." (PMID 28978341, 2017). "Amplification of the Epidermal Growth Factor Receptor (EGFR) gene, observed in 50% of GBMs, creates a tumor-specific target for experimental treatment." (PMID 29075855, 2017). "We postulate that the overexpression of Reg3g increases EGFR, but suppresses tumor antigenicity by upregulating the levels of Ki67 and inhibiting the expression of caspase-3 and MHC-I in tumors." (PMID 28880262, 2017). "In each context, EGFR and Axl inhibition promoted increased tumor cell death, as well as inhibited tumor cell growth." (PMID 27611946, 2017). "CHMFL-EGFR-26 bore acceptable pharmacokinetic properties and demonstrated dose-dependent tumor growth suppression in the H1975 (EGFR L858R/T790M) and PC-9 (EGFR del19) inoculated xenograft mouse models." (PMID 28407693, 2017). "Sections of primary tumour excised together with normal pancreatic tissue, duodenum and stomach, as well as sections of lung were stained for human Cx43 or human epidermal growth factor receptor (EGFR) as a human PDAC marker." (PMID 28368405, 2017). "EGFR signaling contributes to tumorigenesis and tumor progression of CRC and EGFR-targeted cetuximab is used to treat CRC." (PMID 28060743, 2017). "Tumor heterogeneity also played an important role in the progression of oncogene-driven EGFR-TKIs treated cancers." (PMID 29245913, 2017). "As an acquired resistance mechanism of EGFR-TKIs, EMT was firstly revealed in a study from an analysis of tumor biopsies of 37 NSCLC patients who developed resistance to EGFR-TKIs." (PMID 29163853, 2017). "Labelling of the natural ligand, EGF, with 68Ga31 or 18F 32 enabled specific imaging of EGFR-expressing xenografts with tumour-to-blood ratios in the range of 2–5." (PMID 28729680, 2017). "A three-dimensional (3D) culture system was used to simulate the tumour microenvironment affected by lnc-EGFR." (PMID 28541302, 2017). "Epidermal growth factor receptor (EGFR), which is over-expressed in about 50% of TNBCs, is related to boosting tumor growth and increasing metastasis rates, and representing poor clinical outcomes." (PMID 28531218, 2017). "Tumor pathology and genotyping are often determined prior to commencing first-line EGFR-TKI treatment." (PMID 28496005, 2017). "Theliatinib, a novel EGFR TKI with strong affinity to wild type EGFR protein demonstrated dose-dependent anti-tumor activity in a panel of PDECX models with a generally good correlation between EGFR H score and tumor growth inhibition." (PMID 28881608, 2017). "Discordance in the detection of EGFR and KRAS mutations between the primary tumor and corresponding metastases has been shown to be as high as 28% and 24% in 25 patients with metastatic NSCLC, respectively." (PMID 29290998, 2017). "Cetuximab inhibits the proliferation of tumor cells expressing EGFR and increases the cytotoxic activity of chemotherapy and radiotherapy." (PMID 28423516, 2017).